CRP (C-reactive protein)
Diseases named in the same sentence as CRP in open-access papers (continued):
Sharing a sentence is not in itself a finding about the gene and the disease.
psychosis (continued). "Currently, evidence found via meta-analyses is still inadequate to use CRP as an accurate predictor to determine the status of which high-risk individuals would “convert” into psychosis." (PMID 34884840, 2021). "Several meta-analyses have reported that patients with psychotic disorders have higher CRP levels than healthy individuals; however, the cause–effect relation is unclear." (PMID 35059135, 2021). "Inability to distinguish meaningful sensory stimuli from others, known as sensory gating deficit, has also been associated with elevated CRP levels in psychosis." (PMID 34884840, 2021). "In this study, we aimed to examine the longitudinal associations between circulating CRP levels and subsequent risk of psychotic disorders by carrying out a systematic review and meta-analysis of population-based prospective studies." (PMID 34050185, 2021). "In conclusion, this meta-analysis of four prospective, population-based studies provides some evidence for a longitudinal association between high CRP levels (>3 mg/L) at baseline and greater risk for developing psychosis at follow-up." (PMID 34050185, 2021). "A number of population-based studies have reported a longitudinal association between higher CRP levels at baseline and risk of psychosis at follow-up28–34." (PMID 34050185, 2021). "We provide some evidence for a longitudinal association between high CRP levels at baseline and increased risk of psychosis at follow-up." (PMID 34050185, 2021). "Using the longitudinal Northern Finland Birth Cohort 1986 study, we examined the associations of maternal prenatal C-reactive protein (CRP) levels with psychosis risk factors in adolescent offspring." (PMID 33202018, 2021). "We have recently shown an inverse association between the serum level of CRP and cognitive performance in the acute phase of psychosis." (PMID 30394240, 2019). "There is evidence that elevated CRP in adolescence is associated with increased risk of psychosis later on in life." (PMID 29544672, 2018). "Within the patient cohort GDF15 levels were evaluated for association with age, gender, lifestyle factors, C-reactive protein levels, psychosis severity and metabolic disorder." (PMID 28801589, 2017). "Alternatively, as both CT and psychosis are independently associated with elevations in IL-6 and CRP, it can be hypothesized that their overexpression may favour a negative feedback effect with consequent reduction of their production." (PMID 41049865, 2025). "Finally, by evaluating serum levels of calcium, phosphorus, and PTH in addition to vitamin D and CRP, we aimed to find a new cause for starting psychotic disorders and discovering a screening tool for differentiating chronic with new-onset psychotic disorders." (PMID 37803327, 2023). "This study further demonstrated that CRP levels were highly associated with psychotic disorders." (PMID 37803327, 2023). "For instance, it has been proposed that a genetic predisposition for a decreased acute phase response (as reflected by lower CRP levels) might increase the risk of psychosis by increasing susceptibility to infection." (PMID 34050185, 2021). "Our findings, that dichotomous CRP levels (>3 mg/L) could be longitudinally associated with a higher risk of psychosis, are consistent with evidence from previous cross-sectional studies." (PMID 34050185, 2021). "Association of CRP with symptoms commonly shared between mood and psychotic disorders, such as auditory hallucinations and anhedonia, could be one explanation for the apparent trans-diagnostic effect of inflammation." (PMID 33229033, 2021). "Our findings also suggest that association of CRP with symptoms commonly shared between mood and psychotic disorders, such as auditory hallucinations and anhedonia, could be one explanation for the apparent trans-diagnostic effect of inflammation." (PMID 33229033, 2021).
psychosis (continued). "Therefore, in the future larger samples will be required before definitive conclusions can be drawn about the true existence of longitudinal associations between CRP and psychosis risk, and the potential effects of age of onset." (PMID 34050185, 2021). "For instance, our findings suggest that association of CRP with symptoms commonly shared between mood and psychotic disorders, such as auditory hallucinations and anhedonia, could be one explanation for the apparent trans-diagnostic effect of inflammation." (PMID 33229033, 2021). "Furthermore, although scarce, evidence exists for elevated CRP levels being associated with increased mortality in various psychiatric disorders including psychosis." (PMID 34884840, 2021). "Interestingly, a study in Finland elucidated the role of elevated maternal CRP levels in increasing the risk of psychosis in the offspring." (PMID 34884840, 2021). "Out of all 599 admissions, the prevalence of inflammation (serum CRP >3 mg/L) in the ICD-10 diagnostic groups of psychotic disorders (F20–29), mood disorders (F30–39), neurotic disorders (F40–48) and personality disorders (F60–69) was 32%, 21%, 22% and 42%, respectively." (PMID 29544672, 2018). "We hypothesized that plasma GDF15 levels would be (i) increased in psychosis, (ii) elevated by metabolic comorbidity, (iii) associated with CRP levels in patients." (PMID 28801589, 2017). "The main aim of our study was accordingly to investigate the association between the CRP level and cognitive performance in a clinically representative sample of patients with psychosis acutely admitted to hospital, with repeated measurements in the acute phase." (PMID 26973142, 2016). "The same predisposition might also be inherited to the offspring leading to both higher CRP and increased risk for psychosis." (PMID 25781172, 2015). "We tested if baseline levels of immune markers previously linked to psychotic symptoms or treatment response (CRP, IL-1RA, sIL-2R, sTNFR1, sgp130) predicted 10-year outcomes in a first-episode psychosis sample (N = 320), and whether associations were moderated by baseline cannabis use." (PMID 40813774, 2025). "First, previous observational studies that directly measured CRP in case/control cohorts could be confounded because of a variety of variables including lifestyle and general health or could even be caused by factors related to psychosis and/or SZ itself." (PMID 35385317, 2022). "However, cross-sectional studies cannot ascertain the direction of the association, i.e., whether elevated CRP predates or follows psychosis." (PMID 34050185, 2021). "The aims of the present study were to determine if plasma GDF15 levels (i) were different in psychosis patients compared to healthy controls, (ii) associated with severity of psychotic illness, and (iii) associated with degree of metabolic comorbidity and CRP levels in the patients." (PMID 28801589, 2017). "It has been also observed that key stress-related biomarkers, such as cortisol, norepinephrine, and DHEA, as well as cytokines and C-reactive protein, show individual alterations in psychosis." (PMID 40666432, 2025). "Patients with first-episode psychosis have shown increased levels of inflammatory markers, particularly tumour necrosis factor-α and CRP, especially patients exposed to early life adversity." (PMID 41281897, 2025). "The most commonly-studied immune markers in psychosis research are peripheral cytokines and markers of chronic low-grade inflammation (e.g., C-reactive protein)." (PMID 36946486, 2024). "They found significantly elevated C-reactive protein (CRP) levels and interleukin 6 (IL-6) in the psychosis group compared to the controls unaffected by psychosis." (PMID 38911703, 2024). "A systematic review and meta-analysis of prospective cohort studies, involving 89 792 participants, looked into the connection between CRP levels and the subsequent development of psychotic disorders." (PMID 39273641, 2024).
psychosis (continued). "Although we found the highest CRP in the group with the lowest estimated premorbid IQ, this was cross-sectional and it therefore cannot be concluded that high CRP was present before psychosis onset and related to compromised IQ." (PMID 35177144, 2023). "More studies with larger samples and multiple testing during patient admission or follow-up are needed to assess vitamin D and CRP levels in other psychotic disorders." (PMID 37803327, 2023). "A review of the available literature revealed that limited studies have compared vitamin D and CRP serum levels between newly diagnosed psychotic patients and patients in their chronic phases of psychosis." (PMID 37803327, 2023). "Using CRP as a binary variable, we report an increase of 50% in the odds of developing psychosis for those with high (>3 mg/L), as compared to low (≤3 mg/L), CRP levels at baseline in unadjusted analyses." (PMID 34050185, 2021). "However, this epidemiological evidence is at odds with recent findings from Mendelian randomization (MR) studies that used genetic variants as proxies for CRP to examine whether the CRP-psychosis association is likely to be causal or could be attributable to confounding." (PMID 34050185, 2021). "The overall pooled OR for psychosis for CRP ≥1 mg/L as compared to <1 mg/L was 1.18 (95% CI, 0.88–1.59, p = 0.26)." (PMID 34050185, 2021). "The meta-analytic unadjusted OR for psychosis at follow-up in participants with high CRP (>3 mg/L) as compared to low CRP (≤3 mg/L) at baseline was 1.50 (95% CI, 1.09–2.07, p = 0.01)." (PMID 34050185, 2021). "The studies had an average follow-up length of 14.55 years (SD = 7.58) for psychosis after CRP assessment at baseline." (PMID 34050185, 2021). "Compared to those with low baseline CRP (<1 mg/L), the OR for psychosis at follow-up was 0.93 (95% CI, 0.68–1.27) for medium (1–3 mg/L) and 1.49 (95% CI, 0.95–2.32) for high (>3 mg/L) CRP." (PMID 34050185, 2021). "This is puzzling, given that case-control studies have consistently reported higher CRP levels in psychosis patients, and further research is required to understand the exact mechanisms." (PMID 34050185, 2021). "The meta-analytic unadjusted OR for psychosis at follow-up per SD increase in baseline CRP as a continuous value was 1.11 (95% CI, 0.93–1.34, p = 0.24)." (PMID 34050185, 2021). "Our sample included a total of 494 incident cases of psychosis, of which 114 had high CRP levels at baseline (>3 mg/L), which represents 23% of the psychosis sample." (PMID 34050185, 2021). "These beneficial effects can be explained by (i) the pathologic elevation of blood interleukin-6 and C-reactive protein levels in psychotic disorders, and (ii) IFX’s ability to reduce these elevated levels." (PMID 32390850, 2020). "For example, a previous study in this cohort reported higher levels of inflammatory cytokines Interleukin 6 and C Reactive Protein to be related to psychosis, and there are a number of other factors that influence these pathways." (PMID 33067055, 2020). "Trait markers which differentiate psychosis patients from healthy controls throughout the illness course were increased CRP, CCL2, and IL1RA, and decreased KA and KA/Kyn." (PMID 32010121, 2019). "After exclusion of participants with CRP values above 10 μg/ml, data was available for 39 healthy controls, 29 siblings, 11 ultra-high risk (UHR) and 38 psychosis patients." (PMID 31276524, 2019). "The main aim of this study was therefore to investigate how the CRP level in the first acute phase of psychosis correlates with cognitive function during a 6 months follow-up." (PMID 30394240, 2019). "We aimed to investigate how the serum level and initial change of CRP in acutely admitted patients with psychosis was correlated with cognitive performance during a 6-months follow-up period." (PMID 30394240, 2019). "Here, we assess CRP as a marker of inflammation in two independent samples of patients with psychosis." (PMID 30364161, 2018).
psychosis (continued). "There is also evidence indicating a relationship between CRP and cognitive dysfunction in subjects with psychosis." (PMID 30766494, 2018). "CRP is an indicator of inflammation which can be present at chronic low level in psychosis patients especially in those with metabolic comorbidity, which is common particularly in those who undergo certain anti-psychotic drug treatments." (PMID 28801589, 2017). "In the present study we did not detect a significant correlation between GDF15 levels and CRP levels within the psychosis patients." (PMID 28801589, 2017). "The aim of the present study was to investigate possible associations between the level of the inflammation marker C-reactive protein (CRP) and cognitive performance in patients through the acute phase of psychosis." (PMID 26973142, 2016). "For example, studies of participants with 22q11.2 deletion syndrome (22q11.2DS) (a neurogenetic disorder whose phenotype includes both immunodeficiency and ID/psychotic disorder) found higher levels of inflammatory markers (C-reactive protein, IL-6, IL-10, TNFα) compared with healthy individuals." (PMID 40869088, 2025). "In addition, we aimed to investigate the long-term effects of psychosis on these markers by comparing the serum levels of CRP, vitamin D, and its related markers in first-episode psychotic and chronic psychotic patients." (PMID 37803327, 2023). "High levels of CRP in patients with long-term psychosis could also be because of the long-term inflammatory processes caused by their chronic illness." (PMID 37803327, 2023). "Based on random effect meta-analysis of 89,792 participants (494 incident cases of psychosis at follow-up), the pooled odds ratio (OR) for psychosis for participants with high (>3 mg/L), as compared to low (≤3 mg/L) CRP levels at baseline was 1.50 (95% confidence interval [CI], 1.09–2.07)." (PMID 34050185, 2021). "However, these analyses included a limited number of cases of psychosis, and the results using CRP as continuous or categorical variables were largely null." (PMID 34050185, 2021). "Databases were searched for prospective studies of CRP and psychosis." (PMID 34050185, 2021). "It is possible that the CRP-psychosis association is non-linear, as we observe an association using CRP as a binary variable but not using CRP as a continuous variable." (PMID 34050185, 2021). "This study was not able to examine if cannabis use is a mediator of any association between maternal immune activation and offspring psychotic disorders, due to lack of association between prenatal CRP and offspring PEs in our sample." (PMID 33202018, 2021). "Plasma levels of high-sensitivity C-reactive protein (hs-CRP) and myeloperoxidase (MPO) were higher (p<0.05, p<0.001) in patients with psychotic disorders than in HC, and hs-CRP and MPO were independently associated with atherogenic lipid ratios in the multivariable analyses." (PMID 32754070, 2020). "What remains unresolved, however, is whether the levels and change of CRP in the initial phase of acute psychosis influence cognition in later phases." (PMID 30394240, 2019). "We have shown that initial changes in the serum level of CRP in the acute phase of psychosis may predict cognitive function in later phases of the disease." (PMID 30394240, 2019). "In agreement with this latter hypothesis, an add-on trial in patients with psychotic disorders showed that those with increased CRP levels had the largest response to add-on Aspirin as compared to those with lower levels." (PMID 30655509, 2019). "Besides the classical risk factors, also elevated total white blood cell count and CRP levels have been associated with increased CVD risk, and increased CRP levels have been associated with mortality in psychotic disorders." (PMID 30483163, 2018). "Other studies suggest that CRP may be particularly elevated during exacerbations of psychosis and may decrease following resolution of an acute psychotic episode." (PMID 30364161, 2018).
psychosis (continued). "In the largest meta-analysis on CRP levels and psychotic disorders, CRP levels were increased in both drug-naïve and unmedicated patients, as well as after the onset of psychosis, although one study with only drug-naïve FEP patients did not detect any difference in CRP between cases and controls." (PMID 30483163, 2018). "Existing studies have reported an association of CRP with negative symptoms, general psychopathology and cognitive dysfunction in patients with psychosis." (PMID 33229033, 2021). "However, to our knowledge no population-based studies have examined the association between CRP and positive and negative symptoms of psychosis in a general population-based sample." (PMID 33229033, 2021). "Previous studies have reported an association of CRP with negative symptoms, general psychopathology and cognitive dysfunction in patients with psychosis." (PMID 33229033, 2021). "Furthermore, an association between CRP levels and positive symptoms but not negative symptoms of psychosis was found." (PMID 26973142, 2016). "The main finding of the present study was an inverse relationship at baseline between serum levels of CRP and overall cognitive performance, as well as for the subdomains Delayed memory and Attention, in a clinically relevant sample tested in the acute phase of psychosis." (PMID 26973142, 2016). "A psychosis signature (ρ = 0.27; P = .002) differentiated ROP from CHR-P with elevated IL-6, TNF-α, and reduced CRP, alongside GMV shifts in corticothalamic circuits." (PMID 41405910, 2025). "In first episode of psychosis patients (FEP), the correlation between CRP and FA was observed for both the left ILF and left SLF, but this observation is likely a result of the correlation between FA of the left SLF and left ILF in FEP (ρ = 0.665, p = 0.0019)." (PMID 36675612, 2023). "Epidemiological studies have shown that elevations in maternal C-reactive protein (CRP) and pro-inflammatory markers, such as cytokines IL-8 and TNFα, in addition to elevations in IL6 in childhood, predict psychotic disorder." (PMID 27650124, 2016). "Youth with subthreshold psychosis had similar levels of CRP compared to youth without psychosis (Hedge’s g = 0.15, 95%CI(−0.04) −0.33, k = 3, N = 4054, I2 = 58%); however, the data were too heterogeneous for clear meta-analytic interpretation." (PMID 38141839, 2024). "However, the available data for use of PCT in the identification or screening of psychosis is extremely small and further empirical data is necessary to compare the efficacy of PCT against other established biomarkers like CRP." (PMID 34884840, 2021). "Other studies that have assessed CRP in psychotic disorders reported no change after exercise training." (PMID 32709912, 2020). "Elevated CRP in childhood has not been identified as predictive of psychotic disorder or SZ onset in adolescence in one prospective study including 4,500 children." (PMID 30190688, 2018). "Stojanovic and colleagues (2014) studied IL6 and CRP levels in ARMS, psychotic disorder and normal controls and observed elevated IL6 in the combined ARMS and psychotic disorder groups compared to controls, and non significant elevations among ARMS who transitioned compared to those who did not." (PMID 27650124, 2016). "Meta-analyses comparing patients with psychotic disorders with healthy controls have shown increased levels of lymphocytes, monocytes, an increased neutrophil/lymphocyte ratio (NLR), and higher concentrations of C-reactive protein (CRP) among the patient group." (PMID 37763150, 2023). "Our meta-analysis found that neutrophil/lymphocyte ratio, TNF, CRP, IL-6, and total WBC were elevated in youth with threshold psychosis compared to youth without threshold psychosis, extending results from adult populations." (PMID 38141839, 2024). "Youth with TPD had higher CRP (Hedge’s g = 0.38, 95%CI0.05 – 0.70, k = 3, N = 219, I2 = 28%) compared to youth without psychosis." (PMID 38141839, 2024).